CYP17A1 (cytochrome P450 family 17 subfamily A member 1)
Description:
A cytochrome P450 monooxygenase involved in corticoid and androgen biosynthesis. Catalyzes 17-alpha hydroxylation of C21 steroids, which is common for both pathways. A second oxidative step, required only for androgen synthesis, involves an acyl-carbon cleavage. The 17-alpha hydroxy intermediates, as part of adrenal glucocorticoids biosynthesis pathway, are precursors of cortisol (Probable). Hydroxylates steroid hormones, pregnenolone and progesterone to form 17-alpha hydroxy metabolites, followed by the cleavage of the C17-C20 bond to form C19 steroids, dehydroepiandrosterone (DHEA) and androstenedione. Has 16-alpha hydroxylase activity. Catalyzes 16-alpha hydroxylation of 17-alpha hydroxy pregnenolone, followed by the cleavage of the C17-C20 bond to form 16-alpha-hydroxy DHEA. Also 16-alpha hydroxylates androgens, relevant for estriol synthesis. Mechanistically, uses molecular oxygen inserting one oxygen atom into a substrate, and reducing the second into a water molecule, with two electrons provided by NADPH via cytochrome P450 reductase (CPR; NADPH-ferrihemoprotein reductase).
Synonyms: CYP17; S17AH; P450C17; CPT7
Tractability: Small molecule: an approved drug acts on it; a structure with a bound ligand is known; a high-quality ligand is known; it belongs to a druggable protein family. PROTAC: a small molecule that binds it is known.
Target class: Cytochrome P450 family 17A; Cytochrome P450; Cytochrome P450 family 17; Enzyme; Cytochrome P450 17A1
Gene: Protein-coding gene on chromosome 10 (102,830,461 to 102,837,501, reverse strand). Ensembl gene ENSG00000148795.
Subcellular location: Endoplasmic reticulum membrane; Microsome membrane
Subcellular location (Human Protein Atlas): Vesicles
Pathways (Reactome):
Metabolism: Androgen biosynthesis; Glucocorticoid biosynthesis
Disease: Defective CYP17A1 causes AH5
Gene Ontology:
Molecular function: heme binding; steroid 17-alpha-monooxygenase activity; oxygen binding; iron ion binding; monooxygenase activity; oxidoreductase activity, acting on paired donors, with incorporation or reduction of molecular oxygen; oxidoreductase activity, acting on paired donors, with incorporation or reduction of molecular oxygen, reduced flavin or flavoprotein as one donor, and incorporation of one atom of oxygen; steroid hydroxylase activity
Biological process: cortisol biosynthetic process; hormone biosynthetic process; progesterone metabolic process; steroid metabolic process; androgen biosynthetic process; glucocorticoid biosynthetic process; sex differentiation; steroid biosynthetic process; hormone metabolic process; olefinic compound metabolic process; primary alcohol metabolic process
Cellular component: endoplasmic reticulum; endoplasmic reticulum membrane; axon; neuronal cell body
Genetic constraint (gnomAD): Loss-of-function variants: 22 observed, 25.15 expected, observed/expected ratio (o/e) 0.87, 90% interval 0.62 to 1.25. The upper end of that interval is the gene's LOEUF score, 1.25, which puts it in group 5 of 6, group 1 being the genes least tolerant of losing a copy. Missense variants: 284 observed, 353.16 expected, observed/expected ratio (o/e) 0.8, 90% interval 0.73 to 0.89. Synonymous variants: 127 observed, 140.42 expected, observed/expected ratio (o/e) 0.9, 90% interval 0.78 to 1.05.
Homologues: Orthologues: chimpanzee CYP17A1 (99% identical), macaque CYP17A1 (94% identical), dog CYP17A1 (79% identical), rabbit CYP17A1 (78% identical), rat Cyp17a1 (68% identical), mouse Cyp17a1 (67% identical), guinea pig CYP17A1 (66% identical), pig CYP17A1 (66% identical), zebrafish cyp17a1 (49% identical), tropical clawed frog cyp17a1 (48% identical).
Diseases named in the same sentence as CYP17A1 in open-access papers:
CYP17A1 is named in the same sentence as 169 diseases in open-access papers, as found by Europe PMC text mining. Sharing a sentence is not in itself a finding about the gene and the disease. The quoted sentences say what the papers report.
prostate carcinoma (109 papers, 1999 to 2025). A carcinoma that arises from epithelial cells of the prostate gland. "Abiraterone acetate is a potent, selective and irreversible CYP17A1 inhibitor and is commonly used in the treatment of prostate cancer, but it can cause various endocrine side effects, especially if not used concurrently with the appropriate treatment." (PMID 40136360, 2025). "In particular, CYP17A1 dysfunction and the subsequent increase in oxidative stress are closely linked to tumorigenesis, especially in hormone-dependent cancers such as prostate cancer." (PMID 40143186, 2025). "For example, in the treatment of prostate cancer,some of the common side effects associated with CYP17A1 inhibitioninclude hot flashes, osteoporosis, and decreased libido." (PMID 37191389, 2023). "Here, they found a certain haplotype of CYP17A1 was associated with prostate cancer mortality, while a different SNP, rs17115149 CYP17A1, was associated with histologic aggressiveness and Gleason scores." (PMID 37435458, 2022). "The gene polymorphisms of CYP24A1 and CYP17A1 have been closely correlated with the risk of liver, lung, stomach, and prostate cancers in a Chinese population." (PMID 34522968, 2021). "CYP17A1 is a key enzyme in the steroidogenic pathway that produces androgens among other steroids, and it is implicated in prostate cancer." (PMID 32660148, 2020). "We next tested the sensitivity of SPRY2‐deficient cells to the CYP17A1 inhibitor abiraterone, which improves the treatment response of prostate cancer patients when combined with standard‐of‐care ADT." (PMID 29540470, 2018). "CYP17A1 SNPs have been implicated with prostate cancer risk." (PMID 37435458, 2022). "In prostate cancer, for instance, CYP17A1 is central for androgen biosynthesis, contributing to producing testosterone and dihydrotestosterone, which drive the growth of prostate tumors." (PMID 40561159, 2025). "Dysregulated steroid hormone production, often mediated by CYP17A1, closely participates in the pathogenesis of multiple cancers: prostate cancer, hormone-sensitive breast cancer, etc.." (PMID 40561159, 2025). "Abiraterone acetate, a notable CYP17 inhibitor, has shown efficacy in treating metastatic castration-resistant prostate cancer, demonstrating the clinical significance of targeting CYP17A1 in managing advanced stages of the disease." (PMID 40561159, 2025). "Abiraterone is a potent, selective, and irreversible inhibitor of cytochrome P-450c17 (CYP17A1), a key enzyme in the steroidogenesis pathway that plays a crucial role in the adrenal glands, testes, and prostate cancer cells." (PMID 40521126, 2025). "Inhibition of CYP17A1 has thus become a targeted strategy to impede androgen synthesis and, consequently, hinder the growth and progression of prostate cancer." (PMID 40561159, 2025). "CYP17A1 is a critical enzyme in the production of androgens, which are involved in prostate cancer development." (PMID 40807256, 2025). "Most drugs that target CYP17A1 in prostate cancer treatment inhibit both reactions, but the product of the first reaction is needed for the synthesis of glucocorticoids." (PMID 40807256, 2025). "CYP17A1 has been extensively explored for its role in hormone-dependent malignancies, such as prostate cancer and hormone-sensitive breast cancer." (PMID 40561159, 2025). "The structural information presented here is instrumental for understanding the functional implications of CYP17A1 in the context of prostate cancer therapy." (PMID 38791216, 2024). "Abiraterone shows better in vitro selectivity profiles compared to ketoconazole, the first CYP17A1 inhibitor used in the treatment of prostate cancer." (PMID 39598525, 2024). "Onepotential target in the fight against prostate cancer is CYP17A1,a critical enzyme that facilitates androgen synthesis." (PMID 39325660, 2024).
prostate carcinoma (continued). "It is through inhibition of CYP17A1 that abiraterone exerts its prostate cancer treatment effect, yet ketoconazole is thought to be less selective, less potent, and has never been shown to demonstrate the same survival benefits as abiraterone." (PMID 39143030, 2024). "Extensive sequential backbone 1H,15N and 13C nuclear magnetic resonance assignments have now been made for oxidized CYP17A1 bound to the prostate cancer drug and inhibitor abiraterone." (PMID 38842434, 2024). "Androgens like testosterone and dihydrotestosterone playa keyrole in prostate cancer progression, making the enzyme CYP17A1, essentialfor androgen synthesis, a crucial therapeutic target." (PMID 39325660, 2024). "In prostate cancer, key roles have been attributed to CYP17A1 and the sustained intra-tumoral synthesis of 5α-dihydrotestosterone, which is a more potent AR agonist than testosterone." (PMID 39682707, 2024). "In humans, the CYP17A1 gene is expressed in the gonads, adrenal glands, and prostate cancer cells, and both 17α-hydroxylase and 17,20-lyase activities are required for sex steroid hormone biosynthesis." (PMID 39682707, 2024). "Abiraterone, a drug used to treat prostate cancer, can block nuclear accumulation of androgen receptors (ARs) which consequently suppresses expression of cyp17a1." (PMID 37398910, 2023). "It has been reported that drugs targeting CYP17A1, a cytochrome P450c17 inhibitor, slow prostate cancer progression." (PMID 38067489, 2023). "The CYP17A1 has an important role in the biosynthesis of dehydroepiandrosterone (DHEA) as the precursor of androgens and overexpression of this enzyme can cause prostate cancer." (PMID 37496005, 2023). "The less commonly studied CYP17A1 isoform is important in diseases such as polycystic ovarian syndrome and prostate cancer." (PMID 37109081, 2023). "CYP17A1 is a key target for the treatment of breast and prostate cancers that proliferate in response to estrogens and androgens." (PMID 37109081, 2023). "Abiraterone acetate, termed abiraterone hereafter, was approved for CRPC treatments in 2011, highlighting the importance of CYP17A1 in prostate cancer management." (PMID 36838665, 2023). "Abiraterone, a pyridine-substituted pregnenolone-derived inhibitor of steroidogenic CYP17A1 used as a first-line treatment of prostate cancer, cross-reacts with human enzymes CYP11B1, CYP21A2, as well as CYP1A1, CYP2C9 and CYP3A45,6." (PMID 37660137, 2023). "Binding of 1 to CYP17A1 was compared to that of abiraterone, a CYP17A1 inhibitor used pharmaceutically as a first-line treatment of prostate cancer that forms a type II Fe—N interaction as evidenced by a shift of the Soret peak to 424 nm." (PMID 37660137, 2023). "Abiraterone, a CYP17A1 inhibitor, is used along with prednisone in patients with castration-resistant and castration-sensitive prostate cancer, yielding improved overall and disease-free survival." (PMID 37908462, 2023). "The medicinalchemistry community has been committed to the discovery and developmentof CYP17A1 inhibitors for many years, particularly for the treatmentof castration-resistant prostate cancer." (PMID 37191389, 2023). "CYP17A1 is also an essential target in the treatment of prostate cancer as its inhibition leads to the lower production of androgen required for tumour cell growth." (PMID 36467577, 2022). "Abiraterone is the only FDA-approved drug used to treat castration-resistant prostate cancer by inhibiting the CYP17A1, where it binds in its active site and permanently disables the enzyme." (PMID 36467577, 2022). "Inhibition of CYP17A1 is an important modality in the treatment of prostate cancer, which remains the most abundant cancer type in men." (PMID 35204665, 2022). "The role of CYP17A1 and CYP17A1 inhibition in prostate cancer chemotherapy is an emerging therapeutic strategy for prostate cancer that functions by suppressing androgen production, as androgen is required for tumor growth." (PMID 34579444, 2021).
prostate carcinoma (continued). "Over the years, CYP17A1 inhibitors, such as abiraterone acetate, which is sold under the brand name Zytiga and is used to treat prostate cancer." (PMID 34579444, 2021). "There are various treatment modalities for various types of cancers, and one such important treatment strategy for prostate cancer is CYP17A1 inhibition." (PMID 34579444, 2021). "The current study sought to identify the efficacy of Morusflavone, in comparison with abiraterone, in interacting stably with CYP17A1, which is a therapeutic target for prostate cancer." (PMID 34579444, 2021). "These compounds were assessed for their binding affinity and inhibition of purified CYP17A1 enzyme and their antiproliferative activity in selected prostate cancer cell lines." (PMID 32660148, 2020). "The V366M mutant also explains the effectiveness of the anti-prostate-cancer drug abiraterone as a potent inhibitor of CYP17A1." (PMID 29710837, 2018). "CYP17A1 is a target for prostate cancer therapy by inhibitor abiraterone (Zytiga by Johnson & Johnson, New Brunswick, USA)." (PMID 29710837, 2018). "Knowledge about the specificity of CYP17A1 activities is of importance for the development of treatments for polycystic ovary syndrome and inhibitors for prostate cancer therapy." (PMID 29710837, 2018). "The V366M mutant also explained the effectiveness of the anti-prostate cancer drug abiraterone as a potent inhibitor of CYP17A1 by binding tightly at the active site in the WT enzyme." (PMID 29710837, 2018). "The CYP17A1 gene regulates sex steroid biosynthesis in humans through 17α-hydroxylase/17,20 lyase activities and is a target of anti-prostate cancer drug abiraterone." (PMID 29710837, 2018). "Orteronel blocks enzyme activities of CYP17A1 in the testis, adrenal gland, and prostatic cancer tissues, resulting in significant reductions of circulating testosterone levels in blood." (PMID 28938672, 2017). "Cytochrome P450 17A1 (CYP17A1) is an important target in the treatment of prostate cancer because it produces androgens required for tumour growth." (PMID 27406023, 2016). "As cell proliferation of prostate cancer in response to androgen steroid, an inhibition of CYP17A1 becomes an alternative approach to inhibit biosynthesis of androgen and support treatment of prostate cancer." (PMID 26682016, 2015). "Currently, CYP17A1 is a target of interest for the treatment of breast and prostate cancer cells that proliferate in response to androgen and estrogen steroids." (PMID 26682016, 2015). "Despite its limitations, this study is the first to investigate CYP17A1 and HSD3B1 polymorphisms in a Nigerian prostate cancer cohort, revealing population-specific genetic features that may inform biomarker development and precision oncology." (PMID 41023281, 2025). "As a result, CYP17A1 has become a target for therapeutic intervention in prostate cancer treatment." (PMID 40561159, 2025). "Cytochrome P450 17A1 (CYP17A1), also known as 17α-monooxygenase or 17α-hydroxylase/17,20-lyase/17,20-desmolase, is essential in steroidogenesis, including androgen biosynthesis, and contributes significantly to prostate cancer pathogenesis." (PMID 41249771, 2025). "Furthermore, the association of pharmacophore modeling and molecular docking suggests the possibility that luteolin interferes with CYP17A1 as a potential mechanism against prostate cancer." (PMID 40143186, 2025). "Androstenedione is a precursor of both estrogens and androgens, and all intermediates of both ∆4 and ∆5 pathways as well as CYP17A1 enzyme can serve as drug targets in the treatment of hormone-sensitive cancers such as prostate cancer (PCa) and breast cancer (BC)." (PMID 39682707, 2024). "The [Ru(tpy)(NN)] scaffold, where tpy is the tridentate 2,2′;6′,2”-terpyridine ligand, and NN are bidentate ligands, has been used for the caging of abiraterone, a human CYP17A1 inhibitor approved for the treatment of prostate cancer (shown as the lavender monodentate ligand in 2)." (PMID 38672458, 2024).
prostate carcinoma (continued). "The inhibition of CYP17A1 has become a crucial therapeutic strategy in the treatment of prostate cancer because it reduces androgen levels, which can slow down the growth and spread of prostate cancer cells." (PMID 36838665, 2023). "Prostate cancer therapy has been at the forefront of CYP17A1 inhibitordevelopment." (PMID 37191389, 2023). "We thus made the hypothesis that gene polymorphisms occurring in CYP17A1, SLCO2B1, and SLCO1B3 could influence AA antitumor activity in advanced prostate cancer." (PMID 36839973, 2023). "Cyp17a1 has been found to be highly expressed in half about of human prostate carcinomas." (PMID 37398910, 2023). "Abiraterone as an approved anti-prostate cancer drug is a CYP17A1 inhibitor." (PMID 37496005, 2023). "A meta-analysis involving over 2400 prostate cancer patients concluded that CYP17A1 rs743572 SNP was not likely to significantly impact the risk for prostate cancer occurrence." (PMID 37435458, 2022). "Therefore, CYP17A1 is an attractive target for the treatment of prostate cancers that proliferate in response to androgens." (PMID 35204665, 2022). "CYP17A1 inhibition is an important therapeutic target for prostate cancer." (PMID 34579444, 2021). "Further preclinical and clinical evaluations of the lead compound Morusflavone are required to evaluate whether it can serve as a potential inhibitor of CYP17A1, which will be a new hope for prostate cancer treatment." (PMID 34579444, 2021). "Since androgens are one of the main driving forces of prostate cancer, other than chemotherapeutic agents such as docetaxel and cabazitaxel, the androgen receptor (AR) and steroid biosynthesizing cytochrome P450 17A1 (CYP17A1) have been the primary targets of PCa treatment." (PMID 34199743, 2021). "The results of this study show that CYP17A1 inhibition by Morusflavone could be an important therapeutic target for prostate cancer." (PMID 34579444, 2021). "CYP17A1 is also a metabolic target for chemotherapy of castration-resistant prostate cancer." (PMID 31533365, 2019). "Overall, due to the limited functionality of CYP17A1 in the prostate cancer models, C21 steroids are more abundant than the C19 steroids, and alternative pathways could contribute to prostatic steroidogenesis." (PMID 30241348, 2018). "Furthermore, alterations of CYP17A1 activity have been described as possible mechanisms of resistance to hormonal treatments in experimental models of prostate cancer." (PMID 27409606, 2016). "CYP17A1 is an important target for the treatment of prostate cancer that proliferates in response to androgens Genetic variation of CPY17A1 was found to be associated with increased risk of prostate cancer." (PMID 27409606, 2016). "CYP17A1 is an enzyme that plays a major role in steroidogenesisand is critically involved in the biosynthesis of steroid hormones.Therefore, it remains an attractive target in several serious hormone-dependentcancer diseases, such as prostate cancer and breast cancer." (PMID 37191389, 2023). "In addition to CYP17A1, another key rate-limiting androgen biosynthesis enzyme, 3β-hydroxysteroid dehydrogenase type 1 (3βHSD1) encoded by HSD3B1, has emerged as a potential driver for therapeutic resistance in prostate cancer." (PMID 36647834, 2023). "The use of cholesterol for de novo steroidogenesis requires the components of the steroidogenic machinery present in the adrenals and gonads, including steroidogenic acute regulatory proteins, CYP11A1 and CYP17A1, which may play important roles in prostate cancer." (PMID 34630112, 2021). "Our results describing the inhibitory effect of curcuminoids on CYP17A1 as well as CYP19A1 indicate that some of the effects of curcuminoids seen in studies on prostate cancer and breast cancer cell lines, may be due to inhibition of steroidogenic cytochrome P450 enzymes." (PMID 31533365, 2019).